PDGFC (platelet derived growth factor C)
Diseases named in the same sentence as PDGFC in open-access papers (continued):
Sharing a sentence is not in itself a finding about the gene and the disease.
myocardial infarction (2 papers, 2024). Gross necrosis of the myocardium, as a result of interruption of the blood supply to the area, as in coronary thrombosis. "They found that the expression of PDGFA, PDGFD and PDGFRB in the infarcted myocardium were increased after myocardial infarction, whereas PDGFB and PDGFC mRNAs were reduced and protein levels at infarcted myocardium were all significantly reduced in the early stage of myocardial infarction." (PMID 39569832, 2024). "In addition, results of an animal study showed that mRNA expressions of PDGFA, PDGFB, PDGFC, PDGFD and PDGFRs exhibited different changes in the infarcted rat heart in the early and late stages after myocardial infarction." (PMID 39569832, 2024).
myxoma (2 papers, 2024 to 2025). A benign soft tissue neoplasm characterized by the presence of spindle and stellate cells, lobulated growth pattern, and myxoid stroma formation. "Macrophages in myxoma were associated with the upregulation of NFKB1, PDGFC, and IL1B, as well as the downregulation of ATP5PB, HSPB1, and IFI27." (PMID 39090109, 2024).
orofacial cleft (2 papers, 2014 to 2016). A disorder of facial skeleton that is characterized by cleft lip and/or cleft palate that result in feeding, speech and hearing problems caused by failures during development. "The gene PDGFC is important for development of the palate with implication in non-syndromic orofacial clefting." (PMID 24962056, 2014).
ovarian carcinoma (2 papers, 2015 to 2022). A malignant neoplasm originating from the surface ovarian epithelium. "However, there were no apparent differences in the protein expression of PDGFA and PDGFC in tumor tissues of ovarian cancer and normal ovarian tissues." (PMID 36199822, 2022). "Intriguingly, the expression levels of PDGF ligands in tumor cells were inconsistent, as PDGFA and PDGFB stained strongly, whereas PDGFC and PDGFD stained weakly in ovarian cancer tumor cells." (PMID 36199822, 2022).
adrenocortical adenomas (1 paper, 2018). "Moreover, PDGFD is highly expressed in human adrenal gland, unlike PDGFA, PDGFB, and PDGFC, and the expression of PDGFD correlates negatively with cortisol secretion in adrenocortical adenomas." (PMID 29551627, 2018).
cholangiocarcinoma (1 paper, 2011). A carcinoma that arises from the intrahepatic biliary tree (intrahepatic cholangiocarcinoma) or from the junction, or adjacent to the junction, of the right and left hepatic ducts (hilar cholangiocarcinoma). "While the liver tumors in PDGFC Tg mice show characteristics of HCC, the tumors in the Pten null model present a mixed phenotype of HCC and cholangiocarcinoma." (PMID 21731504, 2011). "Interestingly, the phenotypes of the tumors are different in these two models with characteristics of HCC in the PDGFC Tg model and with mixed cell characteristics of HCC and cholangiocarcinoma in the Pten null mice." (PMID 21731504, 2011).
chorioamnionitis (1 paper, 2024). A morphologic finding indicating inflammation of the fetal sac membranes. "At the gene level, chorioamnionitis decreased the expression of PDGFC and PDGFRA and increased the expression of MBP, MAG, and MOG, consistent with our finding of decreased MBP at the protein level." (PMID 38200558, 2024).
cleft lip (1 paper, 2009). Congenital defect in the upper lip where the maxillary prominence fails to merge with the merged medial nasal prominences. "Consistent with the absence of cleft lip in Pdgfc−/− mice, the association with PDGFC was found exclusively in the I-CP group in our data." (PMID 19401770, 2009).
Cognitive impairment (1 paper, 2025). Abnormal cognition is characterized by deficits in thinking, reasoning, or remembering. "Similarly, NLRP3 inflammosomes have been implicated in cognitive impairment, whereas PDGFC signaling has been previously known to ameliorate neuroinflammation by blood–brain barrier disruption in mouse models." (PMID 40665476, 2025).
colon cancer (1 paper, 2022). "Altogether, these results indicate the expression of CAFs-derived key transcriptomes (CTHRC1, NTM, and PDGFC) is associated with poor survival prognosis, immunosuppression, tumor progression, and metastasis in human colon cancer." (PMID 35991839, 2022). "In summary, these results indicated that the expression of CTHRC1, FBN2, NTM, PDGFC, and PDLIM3 is associated with tumor progression and metastasis of colon cancer cells." (PMID 35991839, 2022). "This indicated that the expression levels of CTHRC1, FBN2, NTM, PDGFC, and PDLIM3 genes are associated with the modulation of immune and stromal activity in the colon cancer tumor microenvironment." (PMID 35991839, 2022). "Since the upregulated group of CTHRC1, NTM, PDGFC, PDLIM3, and SLC16A3 and the downregulated group of FBN2 genes are consistently correlated with the shorter survival time in TCGA and GEO datasets, we investigated the association of these genes with immune score and stromal scores in colon cancer." (PMID 35991839, 2022). "We found that upregulated group of CTHRC1, NTM, PDGFC, PDLIM3, and SLC16A3 genes are consistently correlated with the shorter survival of colon cancer patients in GSE17536." (PMID 35991839, 2022). "The upregulation of CTHRC1, PDGFC, PDLIM3, NTM, and SLC16A3 and downregulation of FBN2 are correlated with a shorter survival time in colon cancer." (PMID 35991839, 2022). "Interestingly, we found that the expression levels of CTHRC1, FBN2, NTM, PDGFC, and PDLIM3 are positively correlated with the ssGSEA scores of metastatic-promoting genes in colon cancer (Spearman’s correlation test, p < 0.001)." (PMID 35991839, 2022). "Furthermore, the CTHRC1, FBN2, PDGFC, PDLIM3, and NTM genes are positively correlated with the metastatic scores in colon cancer." (PMID 35991839, 2022). "Finally, the expression level of CTHRC1, PDGFC, and NTM genes are consistently altered in colon tumor stroma as well as in the higher CAFs-group of TCGA COAD patients." (PMID 35991839, 2022). "Finally, we validated the expression levels of these key genes in the colon tumor stroma dataset, and we revealed that the CTHRC1, NTM, PDGFC, and FBN2 genes are consistently altered in colon tumor stroma." (PMID 35991839, 2022). "Finally, we investigated the correlation of CTHRC1, FBN2, NTM, PDGFC, PDLIM3, and SLC16A3 with the metastatic scores in colon cancer data." (PMID 35991839, 2022).
Fraser syndrome (1 paper, 2013). Fraser syndrome is a rare clinical entity including as main characteristics cryptophthalmos and syndactyly. "We propose that loss of FREM1 function promotes epidermal blistering in Fraser syndrome as a consequence of reduced PDGFC activity, in addition to its stabilising role in the basement membrane." (PMID 24046351, 2013). "By establishing a link between FREM1, PDGFC growth factor activity and the downstream regulation of molecules that shape ECM remodelling, the authors bring to light a novel mechanism for the development of basement membrane fragility and blistering in Fraser syndrome and its related diseases." (PMID 24046351, 2013).
head and neck squamous cell carcinoma (1 paper, 2015). A squamous cell carcinoma that arises from any of the following anatomic sites: lip and oral cavity, nasal cavity, paranasal sinuses, pharynx, larynx, and salivary glands. "Other genes identified in the current study which may contribute to the cisplatin resistance of A2780cis included up-regulation of PDGF isoforms such as PDGFC which has been previously linked to cisplatin resistance in head and neck squamous cell carcinoma cell lines." (PMID 26205780, 2015).
liver disease (1 paper, 2024). "The PDGFC gene, a member of the platelet-derived growth factor family and its association with liver diseases has been broadly studied." (PMID 38768139, 2024). "Consequently, our findings provide novel evidence suggesting that an increased interaction of PDGFC and PDGFRA between stellate cells with cholangiocytes, as well as myeloid cells, is associated with liver disease progression and enhanced fibrotic damage." (PMID 38768139, 2024).
lymph node metastasis (1 paper, 2021). "PDGFC significantly associated with the tumor stage, lymph node metastasis and recurrence." (PMID 33918816, 2021).
mammary adenocarcinoma (1 paper, 2025). "A recent study on mammary adenocarcinoma showed that perivascular LYVE1+ TAMs secrete the platelet-derived growth factor-C (PDGF-C) homodimer, PDGF-CC, which signals to PDGF receptor-α (PDGFRA)-expressing stromal cells involved in blood vessel formation." (PMID 41203997, 2025).
Nephropathy (1 paper, 2024). A nonspecific term referring to disease or damage of the kidneys. "PDGFC is potentially involved in periapical lesion pathogenesis through inflammation and contributes to complications in type 2 diabetes, including diabetic foot, microangiopathy, and nephropathy." (PMID 38460073, 2024).
non-small cell lung carcinoma (1 paper, 2024). A group of at least three distinct histological types of lung cancer, including non-small cell squamous cell carcinoma, adenocarcinoma, and large cell carcinoma. "Besides, PDGFC knockdown remarkably decreases non-small cell lung cancer cell proliferation." (PMID 38167429, 2024).
ovarian serous cystadenocarcinoma (1 paper, 2018). A malignant serous cystic epithelial neoplasm arising from the ovary. "Recent studies have shown that FBXL7 expression was positively correlated with CD44, PDGFA, PDGFC, and PDGFD in ovarian serous cystadenocarcinoma." (PMID 30301218, 2018). "The results showed that FBXL7 expression was positively correlated with CD44, PDGFA, PDGFC, and PDGFD in ovarian serous cystadenocarcinoma tissues with a statistical significance (p = 0.001 or p < 0.001)." (PMID 30301218, 2018). "In addition, FBXL7 expression was positively correlated with CD44, PDGFA, PDGFC, and PDGFD in ovarian serous cystadenocarcinoma." (PMID 30301218, 2018).
thyroiditis (1 paper, 2009). Inflammation of the thyroid gland. "Thus, we find that PDGFC mRNA expression were down-regulated in biopsies containing infiltrated lymphocytes or thyroiditis." (PMID 19968886, 2009).
Ureteral obstruction (1 paper, 2023). Obstruction of the flow of urine through the ureter. "In rats with unilateral ureteral obstruction, salvianolic acid B improves kidney dysfunction; increases the expression of PAR-3 polyclonal antibody (Par-3); and reduces the expression of connective tissue growth factor (CTGF), platelet-derived growth factor C (PDGF-C), and PDGFR-α." (PMID 37765204, 2023).
tumor (85 papers, 2008 to 2025). "Consistently, a positive correlation was identified between PDGFC and biomarkers of the N2 state of tumor-associated neutrophils." (PMID 40501228, 2025). "BRAF upregulation correlates with PDGFC mutation, which promotes tumor growth, survival, angiogenesis, and metastasis." (PMID 41009348, 2025). "PDGFC encodes a platelet-derived growth factor that has an anti-apoptotic role in tumor-associated macrophages, thus contributing to tumorigenesis and malignant inflammation." (PMID 33972406, 2021). "PDGFC encodes platelet derived growth factor C33 and is upregulated during hypoxia in tumor cells." (PMID 36721044, 2023). "At least in part, this likely reflects the activated microenvironment associated with macrometastatic lesions as Pdgfc or PDGFC expression by ER+ tumor cells could be induced by co-culture with PDGF-Chi CAFs." (PMID 36914817, 2023). "We characterized and compared ECM protein changes occurring during tumor development in the PDGFC Tg mouse model, a model of HCC associated with fibrosis and angiogenesis and in the Pten null mouse model, a model of liver tumors of mixed cholangio- and hepatocytic features." (PMID 21731504, 2011). "In the TME, elevated PDGFC expression promotes the transition of normal fibroblasts (NFs) into CAFs, thereby significantly influencing tumor growth, migration, invasion, and the development of drug resistance." (PMID 41213930, 2025). "On the other hand, some tumor fibroblasts increase the production of platelet-derived growth factor-C (PDGF-C)." (PMID 40341988, 2025). "Overall, these data suggested that CAF-derived PDGFC promoted tumor progression through the induction of immune suppression in the TME." (PMID 40501228, 2025). "Evidence indicates that PDGFC secreted by tumor cells facilitates the lung colonization of BC cells and activates pulmonary fibroblasts, promoting distant tumor dissemination and progression." (PMID 41213930, 2025). "In particular, PDGFC induces increased PDGFRA expression in both tumor cells and fibroblasts, which can lead to reciprocally positive feedback to accelerate malignant tumor progression." (PMID 40501228, 2025). "Literature evidence suggests that activation of AKT signaling in cancer cells can upregulate PDGFC expression, and PDGFC secreted by tumor cells can activate fibroblasts." (PMID 41213930, 2025). "CAFs can promote tumor cell mitotic proliferation via PDGFC/PDGFRA/SLUG, achieving metastasis and immune escape by regulating E2F, signal transducer and activator of transcription 5 (STAT5), etc.." (PMID 39015573, 2024). "The sequencing data showed that the expression of PDGFC was significantly increased in PDAC tumor tissues." (PMID 39225567, 2024). "High PDGFRA and PDGFC expression can promote tumor proliferation, angiogenesis, migration, and invasion." (PMID 36979654, 2023). "Elevated expression of PDGFC in CAFs promoted tumor growth and metastasis via the enhanced SLUG-mediated EMT12." (PMID 33568624, 2021). "In turn, PDGFC-PDGFRA signal transduction promotes tumor growth and metastases via regulation of SLUG expression." (PMID 33603171, 2021). "In chemotherapy-resistant tumors, increased expression of platelet-derived growth factor-c (PDGF-c) by CAFs contributes to tumor angiogenesis during anti-VEGF therapy." (PMID 34294146, 2021). "These PDGFRα+ OPCs are recruited at the tumor border through PDGFC released by TME cells, including TAMs." (PMID 34690699, 2021). "The half-lives of angiogenic mRNAs, including ENG, EDN1, VEGFB and PDGFC, were reduced approximately 2-fold in Roquin2-overexpressing tumor cells compared to the control group." (PMID 34345214, 2021). "Additionally, exogenous PDGFC and co-culture systems were used to investigate the effects of tumor cell-derived PDGFC on fibroblasts." (PMID 41213930, 2025).
tumor (continued). "Importantly, PDGFC induces increased PDGFRA expression in both tumor cells and fibroblasts, which leads to reciprocally positive feedback, accelerating the fibrotic TME and malignant progression of tumors." (PMID 40501228, 2025). "Notably, the results of the IHC analysis also indicated that PDGFC was primarily localized in the tumor stroma." (PMID 40501228, 2025). "Furthermore, we observed that PDGFC knockdown increased the apoptotic rate of PDAC cells, indicating the anti‐tumor effect of PDGFC inhibition." (PMID 39225567, 2024). "Moreover, we observed a significant upregulation of PDGFC expression in both tumor tissues and liver metastasis." (PMID 39225567, 2024). "Additionally, there was also a notable reduction in tumor weight after PDGFC silencing compared to the control group." (PMID 39225567, 2024). "PDGFC is expressed in tumor cells including glioblastoma and lung carcinoma." (PMID 36979654, 2023). "Similarly, tumor cell PDGFC, assessed using a human-specific PDGFC probe, was upregulated in ER+ ZR-75-1 tumors compared to ZR-75-1 cells in culture." (PMID 36914817, 2023). "CAFs produce angiogenesis regulators, such as VEGFA, PDGFC, FGF2, CXCL12, osteopontin, and CSF3 to promote the growth of tumor-associated blood vessels by recruiting myeloid cells and accelerate tumor angiogenesis by attracting vascular endothelial cells and recruiting monocytes." (PMID 37784082, 2023). "Indeed, PDGFC also activates PDGFC-α signal transduction in gastrointestinal stromal tumor cells and manages the expression of slug and downstream targets, stimulating cancer cell proliferation and metastasis in a paracrine manner." (PMID 35422475, 2022). "Moreover, using IHC staining performed on TMAs, we further perform survival analyses of PDGFC and validated it expression differences between tumor and adjacent normal tissue." (PMID 35422475, 2022). "Consequently, these results provide evidence that PDGFC overexpression is responsible for FTO-mediated tumor progression." (PMID 35422475, 2022). "Interestingly, mice with either PDGFRA or PDGFC deletion display a normalized vascular network and a significant decrease in tumor volume." (PMID 34690699, 2021). "However, in an environment with high PDGFC levels, such as in old or fibrotic lungs, it could trigger the proliferation of tumor cells." (PMID 39225567, 2024). "Additionally, PDGFC acts directly on tumor cells and promotes their proliferation." (PMID 35422475, 2022). "Besides, we also observed that overexpression of EDN1 and PDGFC could reverse the inhibitory effects of Roquin2 on tumor angiogenesis in vitro and in vivo." (PMID 34345214, 2021). "Moreover, PDGFC mRNA was highly expressed in all GIST-derived CAFs versus tumor cells." (PMID 33603171, 2021). "In addition to VEGF, FGF-2, ANG-2, HIF-2α, and PDGFC are also involved in tumor angiogenesis." (PMID 21843314, 2011). "Surprisingly, we found that ESM1 and PDGFB are expressed in the same tumor regions, while the distributions of PDGFA and PDGFC seem to be mutually exclusive with those of PDGFB and ESM1." (PMID 39773984, 2025). "In particular, PDGFC is crucial for immune suppression in the TME, which further promotes tumor progression." (PMID 40501228, 2025). "To further validate the roles of NRG1 and PDGFC in promoting PTX resistance in BC in vivo, we established ectopic tumor models using nude mice." (PMID 41213930, 2025). "CAF release pro-angiogenic factors such as VEGFA, PDGFC, and FGF2 to stimulate or adversely affect angiogenesis in tumor tissues." (PMID 40485724, 2025). "Studies suggest that FB can secrete various factors, including VEGFA, PDGFC, FGF2, and osteopontin, which are known to stimulate angiogenesis in tumor tissues." (PMID 39759522, 2024). "Taken together, these findings offer compelling evidence that PDGFC knockdown substantially inhibits the malignant progression of PDAC, supporting its potential as a promising marker for predicting tumor progression." (PMID 39225567, 2024).